L1CAM (L1 cell adhesion molecule)
Diseases named in the same sentence as L1CAM in open-access papers (continued):
Sharing a sentence is not in itself a finding about the gene and the disease.
ischemia (1 paper, 2024). A hypoperfusion of the BLOOD through an organ or tissue caused by a PATHOLOGIC CONSTRICTION or obstruction of its BLOOD VESSELS, or an absence of BLOOD CIRCULATION. "The L1 cell adhesion molecule (L1) has demonstrated a range of beneficial effects in animal models of spinal cord injury, neurodegenerative disease, and ischemia; however, the role of L1 in TBI has not been fully examined." (PMID 38474289, 2024).
leiomyoma (1 paper, 2021). A well-circumscribed benign smooth muscle neoplasm characterized by the presence of spindle cells with cigar-shaped nuclei, interlacing fascicles, and a whorled pattern. "Most of the leiomyoma DEGs were found upregulated in F compared to the MF or M; however, some genes, including CDKN1A, L1CAM, SLC7A5, CCND1, IGF1R, and PTHLH, were only increased in MF vs. M and F vs. M comparisons." (PMID 33807176, 2021).
leukemia (1 paper, 2023). A malignant (clonal) hematologic disorder, involving hematopoietic stem cells and characterized by the presence of primitive or atypical myeloid or lymphoid cells in the bone marrow and the blood. "Further experiments using CCRF-CEM and MOLT-3 T-ALL leukemia cell lines, corroborated upregulation of STAT-1 and L1CAM after treatment with NKG2D-CAR T cells." (PMID 37928520, 2023).
Lewy body disease (1 paper, 2020). "In 226 subjects (18 RBD, 77 PD, 36 PDD, 11 DLB, 69 HC, 15 FTD), we also asked whether elevated α-synuclein in Lewy body disease is phosphorylated at serine 129 (pSer129) in L1CAM-positive exosomes and has a value as a blood-based biomarker." (PMID 32273329, 2020).
liver cancer (1 paper, 2023). An epithelial or non-epithelial malignant neoplasm that arises from the liver. "As a neuro-adhesion-related molecule, the function of L1CAM in tumor metastasis has been reported, and the MVI status of liver cancer patients is closely related to recurrence and metastasis." (PMID 38049860, 2023).
lung squamous cell carcinoma (1 paper, 2024). "Notably, L1CAM mRNA was expressed to a significantly greater extent in SCLC tissues than in LUAD or lung squamous cell carcinoma (LUSC) tissues." (PMID 39201435, 2024).
lupus (1 paper, 2024).
lysosomal storage disease (1 paper, 2025). A metabolic disorder caused by mutations in proteins critical for lysosomal function, including lysosomal enzymes, lysosomal integral membrane proteins, and proteins involved in the post-translational modification and trafficking of lysosomal proteins. "In our study, intracellular vesicular traffic, immune system, signal transduction, L1CAM interaction, and lysosomal activity pathways were found to be affected, similar to a previous study conducted with mucolipidosis, a lysosomal storage disease." (PMID 40565173, 2025).
malignant pleural mesothelioma (1 paper, 2024). A malignant neoplasm that arises from mesothelial cells in the pleura and shows a diffuse growth pattern. "Using GSEA, six enriched pathways emerged with P.adj<0.05, including the Wnt signaling pathway, G2 M checkpoint, and RNA metabolism, L1CAM interactions, potential therapeutics for Sars, malignant pleural mesothelioma." (PMID 38356701, 2024).
metastatic cancers (1 paper, 2025). A carcinoma which has spread from the original site of growth to another anatomic site. "Interestingly, CDH5, CDH17, and L1CAM share their involvement in several metastatic cancers, which could be related to the pairwise sequence alignment found near the RGD motif for the combinations CDH17/L1CAM and CDH17/CDH5 (its second RGD motif)." (PMID 41039222, 2025).
neonatal encephalopathy (1 paper, 2010).
Nephropathy (1 paper, 2015). A nonspecific term referring to disease or damage of the kidneys. "This study identified that higher PIP, THBS2 and/or NGAL levels were significantly associated with nephropathy of T2DM, and higher L1CAM but normal PIP, THBS2 or NGAL was significantly associated with retinopathy of T2DM." (PMID 27446820, 2015). "Results also showed that L1CAM levels were significantly higher in T2DM with retinopathy but not significantly higher in T2DM without or with nephropathy than in normal adults." (PMID 27446820, 2015). "Further, PIP, THBS2 and NGAL were significantly higher in T2DM patients with nephropathy (albuminuria) but not in those with retinopathy, while L1CAM levels were higher in T2DM patients with retinopathy." (PMID 27446820, 2015). "Neural cell adhesion molecule, L1 (L1CAM) was found to be significantly higher in T2DM patients with retinopathy but not T2DM without or with nephropathy." (PMID 27446820, 2015).
neuroendocrine pancreatic carcinoma (1 paper, 2020). "However, studies in a few other cancers such as childhood neuroblastoma, and neuroendocrine pancreatic carcinoma had shown that increased L1CAM expression is actually linked to favourable outcome." (PMID 32291413, 2020).
oncocytic neoplasm (1 paper, 2025). A usually benign neoplasm composed of large cells with abundant eosinophilic granular cytoplasm. "Our results showed that L1CAM was present only in low-grade oncocytic tumors and not in the other tumor types studied." (PMID 40805143, 2025).
ovarian serous cystadenocarcinoma (1 paper, 2020). A malignant serous cystic epithelial neoplasm arising from the ovary. "In addition, we analyzed the association of L1CAM, vimentin and TGF-β1 expression with the overall survival (Kaplan Meier Plot) from a data set of 300 ovarian serous cystadenocarcinoma tumor samples (The Cancer Genom Atlas, TCGA RNAseq expression, Pan-Cancer Atlas)." (PMID 31952346, 2020).
peripheral nerve injury (1 paper, 2021). Injury to a peripheral nerve. "Here, the L1-CAM-positive hypertrophic varicosities also represented the input sites that received the signals of axo-axonic synapses in the dorsal horn after peripheral nerve injury." (PMID 33500315, 2021).
pituitary tumor (1 paper, 2022). A benign or malignant neoplasm affecting the pituitary gland. "Fittingly, Gal‐3 has been demonstrated to promote proliferation and migration and inhibit apoptosis of pituitary tumor cells reflecting the effect of L1CAM overexpression in RB cells, resulting in increased Gal‐3 levels." (PMID 34228897, 2022).
primary ciliary dyskinesia (1 paper, 2019). A rare, genetically heterogeneous, primarily respiratory disorder characterized by chronic upper and lower respiratory tract disease. "As such, our rat genetics data exclude the human heterozygous CCDC39 mutant allele and heterozygous L1CAM allele from the candidate genetic modifier elements that alter the disease severity of XLH and primary ciliary dyskinesia." (PMID 31771992, 2019).
prostate adenocarcinoma (1 paper, 2014). "We further investigated L1CAM expression in a prostate adenocarcinoma tissue microarray by IHC." (PMID 25294816, 2014).
pulmonary neuroendocrine tumors (1 paper, 2012). "L1 cell adhesion molecule (L1CAM) has potential prognostic value in pulmonary neuroendocrine tumors." (PMID 22292069, 2012).
rectal cancer (1 paper, 2021). A primary or metastatic malignant neoplasm that affects the rectum. "Nevertheless, more studies are required to verify whether SPINK4 can activate L1CAM through PA inhibition to drive metastasis and CCRT resistance in rectal cancer." (PMID 34202399, 2021).
relapsing-remitting MS (1 paper, 2025). "This study aimed to assess whether blood-derived L1CAM+ EVs could serve as biomarkers of treatment response to rituximab (RTX) in patients with relapsing-remitting MS (RRMS)." (PMID 40806340, 2025).
Renal insufficiency (1 paper, 2021). A reduction in the level of performance of the kidneys in areas of function comprising the concentration of urine, removal of wastes, the maintenance of electrolyte balance, homeostasis of blood pressure, and calcium metabolism. "Only one patient in a cohort assessable for HE4 had renal insufficiency, whereas the number of patients evaluable for L1CAM, DJ1 and CA125 having renal insufficiency was higher." (PMID 34203959, 2021).
spinal cord injury (1 paper, 2022). Penetrating and non-penetrating injuries to the spinal cord resulting from traumatic external forces (e.g., WOUNDS, GUNSHOT; WHIPLASH INJURIES; etc.). "The immunoglobulin superfamily molecule L1CAM/CD171, here shortened to L1, was the first CAM that improved recovery after spinal cord injury (SCI) in rats and mice, when administered to injured spinal cords." (PMID 36411762, 2022).
teratoma (1 paper, 2013). A non-seminomatous germ cell tumor characterized by the presence of various tissues which correspond to the different germinal layers (endoderm, mesoderm, and ectoderm). "There were distinct areas of colocalization for SSEA-5 and L1CAM within the teratoma." (PMID 26317026, 2013). "Since SSEA-5 is a marker of teratoma-forming potential for iPSCs, we examined iPSC-induced teratomas for SSEA-5 and L1CAM immunoreactivity." (PMID 26317026, 2013).
thymic carcinoma (1 paper, 2023). Thymic carcinoma (TC) is a type of thymic epithelial neoplasm characterized by a high malignant potential. "L1CAM, another marker of tuft cell differentiation, also showed excellent specificity and moderate sensitivity for thymic carcinoma in the prior study." (PMID 37190202, 2023).
tongue cancer (1 paper, 2021). A malignant neoplasm affecting the tongue. "In the majority of advanced stages of human tongue cancers, clusters of cells strongly positive for L1CAM were visible." (PMID 35008571, 2021).
tongue SCC (1 paper, 2021). "To asses if the expression of L1CAM correlated with the clinical tumor stage of tongue SCC, we performed immunohistochemical stainings of L1CAM on a tissue microarray slide panel." (PMID 35008571, 2021).
tubulinopathy (1 paper, 2019). A nervous system disorder characterized by complex cortical malformations including in most cases dysmorphic basal ganglia and/or corpus callosum in which the cause of the disease is a variation in a tubulin gene. "These included brainstem and cerebellar malformations with specific pathological correlates (absent cerebellar vermis, kinking of the brainstem in L1CAM and tubulinopathy), perisylvian polymicrogyria, subependymal heterotopias and enlarged ganglionic eminences." (PMID 31076826, 2019).
urothelial carcinoma (1 paper, 2013). A malignant neoplasm derived from the transitional epithelium of the urinary tract (urinary bladder, ureter, urethra, or renal pelvis). "In urothelial carcinoma, both L1CAM and SSEA-5 were seen, with many regions of colocalization." (PMID 26317026, 2013).
uveal melanoma (1 paper, 2024). A melanoma derived from melanocytes of the uveal tract. "In uveal melanoma liver metastasis, L1CAM enables cancer cells to attach and utilize existing blood vessels in the liver." (PMID 38737903, 2024). "In addition, compared with angiogenic tumors, the invasive front of uveal melanoma using VC is rich in “L1CAM and laminin vascular network”." (PMID 38737903, 2024).
vascular tumor (1 paper, 2021).
vulvar squamous cell carcinoma (1 paper, 2016). An invasive squamous cell carcinoma arising from the vulva. "In a search for markers that can identify patients at risk of metastases, we investigated the prognostic value of L1-cell adhesion molecule (L1CAM) in large series of vulvar squamous cell carcinomas (VSCCs)." (PMID 27028855, 2016).
vulvar tumour (1 paper, 2016). "Our spheroid invasion assay suggests that the invasion of these spindle shaped vulvar tumour cells can be strongly inhibited by treatment with L1CAM neutralising antibodies." (PMID 27028855, 2016).
tumor (310 papers, 2010 to 2026). "In BC, elevated L1CAM expression has been strongly associated with high tumor grade, lymphovascular invasion, increased metastatic risk, and poor prognosis." (PMID 41306535, 2025). "L1CAM drives UCEC aggressiveness by promoting tumor invasion, drug-resistance and metastasis, and therefore in both high- and low-risk diseases, high L1CAM expression is associated with recurrence and/or local and distant metastasis, and poor outcomes." (PMID 40458122, 2025). "In the last few years many in vitro and in vivo studies have conferred to L1CAM a tumor promoting role and its expression is generally associated with poor prognosis." (PMID 40770187, 2025). "Of interest, L1CAM gene expression is associated with RNA methylation, and its expression controls the immunological tumor response." (PMID 40870967, 2025). "Another study found a significant association between L1CAM expression and tumor invasion and metastasis in KRAS mutant patients." (PMID 40282985, 2025). "L1CAM shows a high positivity rate in CTCs, particularly in H-CTCs, and is strongly associated with tumor aggressiveness." (PMID 41306535, 2025). "pCAFs secrete lactic acid that promotes the lactylation of histone H3K18 in tumor cells, an epigenetic modification that upregulates the neuroinvasion-associated genes L1CAM and SLIT to enhance tumor invasive capacity." (PMID 40565047, 2025). "Lastly, immunohistochemistry analyses supported our transcriptomic findings by showing that L1CAM expression, one of the genes associated with oxaliplatin resistance, was upregulated at both the RNA level in PDOs and protein levels in matched tumor tissues." (PMID 41280668, 2025). "L1CAM (CD171) is known to be closely associated with the epithelial-to-mesenchymal transition as a substance related to tumor cell motility and showed a significant difference between specific survival and OS in EC." (PMID 39734232, 2024). "While its primary functions relate to neuronal migration, axon growth, and synapse formation in the brain, L1CAM has been consistently detected in tumors over the past two decades and is implicated in tumor progression." (PMID 38183514, 2024). "The L1 cell adhesion molecule (L1CAM), a protein highly expressed in various malignant tumors, is closely associated with tumor invasion, metastasis, and poor prognosis." (PMID 39397869, 2024). "Because the perivascular tumor niche is highly associated with metastasis, luciferase-labeled L1CAM overexpressing and control 786-O cells were injected into the tail veins of nude mice (n = 8, each group)." (PMID 37015905, 2023). "L1CAM is associated with aggressive behavior of the tumor (cell migration, invasion, epithelial–mesenchymal transition, and chemoresistance), and predicts worse outcomes (recurrence, reduced survival) in p53wilde-type/NSMP tumors." (PMID 37298731, 2023). "We tested expression of L1 cell‐adhesion molecule (L1CAM), a well‐recognised marker of poor prognosis in EC, in tumour samples from high‐risk EC patients, to explore its role as a predictive marker of Pt‐aCT response." (PMID 35429348, 2022). "Several studies have implicated L1CAM in malignancy-related traits of OC, including epithelial-mesenchymal transition, tumor growth and dissemination, and chemoresistance." (PMID 34645505, 2021).
tumor (continued). "Various chemokines and cytokines in the TME have been reported to play crucial roles in tumor progression, and indeed, when we used the DEGs to perform GO enrichment analysis, we found that L1CAM was associated with immunity and the chemokine pathway." (PMID 33710805, 2021). "L1CAM expression has been associated with poor clinical outcome in a variety of tumours, suggesting a role as prognostic marker 18-20." (PMID 34659530, 2021). "The fact that the majority of the tumors were classified as NSMP underlines the importance of further classification of tumor by use of additional methods such as L1CAM expression and LVSI analysis." (PMID 33467460, 2021). "L1CAM protein expression in tumor tissues was associated with T classification, differentiation, tumor/node/metastasis (TNM) stage, and survival status." (PMID 33710805, 2021). "Upregulation of L1CAM in EC is at least in part caused by the downregulation of L1CAM-targeting tumor suppressor miR-34a." (PMID 34298609, 2021). "Overall, our in vivo assays pointed to a causal role of L1CAM in the tumor initiation capacity of OC cells." (PMID 34645505, 2021). "We retrospectively investigated the impact of the implementation of L1CAM into our risk assessment at the tumour board regarding different risk groups." (PMID 34659530, 2021). "L1CAM interactions found in this study to involve lncRNAs common to WDTC have been previously associated with well-described roles in tumour progression, metastases and the epithelial-to-mesenchymal transition." (PMID 34408227, 2021). "L1 cell adhesion molecule (L1CAM) is aberrantly expressed in several tumor types where it is causally linked to malignancy and therapy resistance, acting also as a poor prognosis factor." (PMID 32429448, 2020). "This suggests that the expression of L1CAM as a CSC-associated marker is tumor type-dependent, and in certain tumors L1CAM can even mark selectively the non-stem cancer cell population." (PMID 32429448, 2020). "Here, we provide comprehensive data demonstrating that downregulation of L1CAM in PDAC is a hallmark of tumour dedifferentiation and enhanced stemness." (PMID 32291413, 2020). "In CRC patients, L1CAM expression has been associated with invasion, tumor progression, poor survival and metastasis." (PMID 33167483, 2020). "In general, L1CAM expression was associated with poor prognosis, tumor progression, and metastasis to lymph nodes in nearly all solid tumors." (PMID 32509846, 2020). "Our data contrast with findings for most other cancers and previous studies on PDAC, where L1CAM expression was associated with poor prognosis, tumour progression and lymph nodes metastasis." (PMID 32291413, 2020). "L1CAM orchestrates different endothelial cell (EC) functions within tumor-associated vessels, such as permeability, pericyte coverage and polarity." (PMID 30829570, 2019). "Similar as in neurons, tumor-associated L1CAM is proteolytically cleaved and soluble ectodomains can be detected in the sera and ascites of ovarian and in the sera of gastrointestinal and breast cancer patients." (PMID 31455004, 2019). "First, L1CAM protein was mainly expressed in tumour cells of GC tissues, and high L1CAM expression was an independent risk factor for both recurrence and survival in the FFPE cohort." (PMID 31754264, 2019).